CLDN1 (claudin 1)
Diseases named in the same sentence as CLDN1 in open-access papers (continued):
Sharing a sentence is not in itself a finding about the gene and the disease.
Chlamydia infection (1 paper, 2019). "We observed a differential distribution of JAM-1, ZO-1, and claudin-1 to the cellular TJs throughout Chlamydia infection that seemed to depend on the functionality of TLR3." (PMID 30625140, 2019).
Cholestatic liver disease (1 paper, 2023). "Since F11r-/- mice are highly susceptible to liver injury and since deficiency of other tight junction proteins, namely tight junction protein 2 and claudin-1, is associated with cholestatic liver disease, to explain the proband ́s phenotype as a consequence of JAM1 deficiency tempted us." (PMID 37471416, 2023).
clostridium difficile infection (1 paper, 2025). Symptomatic infection due to the spore-forming bacterium clostridium difficile. "For example, butyrate enhances the expression of Cldn1 (encoding Claudin-1) and Ocln (encoding occludin) via hypoxia-inducible factor 1 (HIF-1), conferring resistance to barrier disruption and bacterial translocation following Clostridium difficile infection." (PMID 41019075, 2025).
coronary artery disease (1 paper, 2024). "Meanwhile, the levels of ileal tight junction proteins such as claudin-1 and ZO-1 were significantly increased in mice transplanted with healthy donor fecal bacteria compared with those transplanted with coronary artery disease patients." (PMID 39086542, 2024).
crescentic glomerulonephritis (1 paper, 2014). A histopathologic term for a pattern of diseases characterized by extensive crescent formation in the glomeruli; patients present clinically with rapid deterioration of renal function, and possible progression to end-stage renal failure within weeks or months. "Though parietal epithelial cells that were positive in claudin-1 have been demonstrated to be the predominant population of the cellular crescent in the murine model of crescentic glomerulonephritis, it is unclear whether this is true in cellular crescent in human disease." (PMID 24868462, 2014). "We detected claudin-1 staining in the nonjunctional cell membrane and cytoplasm of the cells composing the cellular crescents in crescentic glomerulonephritis." (PMID 24868462, 2014).
cyst (1 paper, 2022). A sac-like closed membranous structure that may be empty or contain fluid or amorphous material. "The expression of claudin-4 in every cyst type was lower than that of claudin-1." (PMID 34808689, 2022).
demyelinating peripheral neuropathies (1 paper, 2018). "In a small study on peripheral nerve biopsies of five patients with demyelinating peripheral neuropathies, claudin-1, and occludin were measured in Western blot and localized by immunolabeling." (PMID 30618565, 2018).
dengue (1 paper, 2023). "Exposure of PLT-EXOs isolated from dengue patients reduced the expression of Claudin-1, CD31 cell adhesion molecules, VE-Cadherin and ZO-2 intercellular junctional proteins of the endothelium and stimulated the excessive release of inflammatory markers from endothelial cells." (PMID 38235130, 2023).
diabetic cardiomyopathy (1 paper, 2021). Diabetic cardiomyopathy is a disorder of the heart muscle in people with diabetes. "The results demonstrated that ZO-1, occludin, and claudin-1 expressions were decreased in the intestinal tissues of diabetic cardiomyopathy mice." (PMID 34084135, 2021).
diarrheal disease (1 paper, 2019). The condition of having at least three loose or liquid bowel movements each day. "Unfortunately, it is not straightforward to test directly whether the contradictory effects of CLDN-1 on CPE action in Caco-2 cells impact CPE toxicity during enterotoxemia or diarrheal disease." (PMID 31601044, 2019).
endometrioid adenocarcinoma (1 paper, 2018). An adenocarcinoma characterized by the presence of malignant glandular epithelial cells resembling endometrial cells. "By evaluating immunohistochemical scores, low claudin-1 and high claudin-2 protein contents were found in hyperplasia and endometrioid adenocarcinoma (type I), whereas in seropapillary adenocarcinoma (type II), high claudin-1 and low claudin-2 levels were detected." (PMID 30061539, 2018).
endothelial dysfunction (1 paper, 2019). In vascular diseases, endothelial dysfunction is a systemic pathological state of the endothelium (the inner lining of blood vessels) and can be broadly defined as an imbalance between vasodilating and vasoconstricting substances produced by (or acting on) the endothelium. "The down-regulation of Cldn1 suggests endothelial dysfunction, which may affect the barrier function of the vascular endothelium." (PMID 31446617, 2019).
enterotoxemia (1 paper, 2019). Disease caused by the liberation of exotoxins of clostridium perfringens in the intestines of sheep, goats, cattle, foals, and piglets. "Compared to wild-type Caco-2 cells, paracellular permeability of the CLDN-1 mutant was significantly enhanced, suggesting that claudin-1 may reduce CPE absorption during enterotoxemia." (PMID 31601044, 2019). "However CLDN-1 also reduces CPE cytotoxicity so it is possible that, during enterotoxemia, this claudin may also inhibit any CPE uptake resulting from intestinal damage." (PMID 31601044, 2019). "CLDN-1 is considered an important structural and functional constituent of TJs in epithelial cells and thus could impact the paracellular permeability of CPE during enterotoxemia, where CPE absorption begins prior to the onset of intestinal damage." (PMID 31601044, 2019).
ependymoma (1 paper, 2017). A WHO grade II, slow growing tumor of children and young adults, usually located intraventricularly. "Furthermore, we could not detect expression of claudin-1 and −2, occludin or E- and N-cadherin in these cases suggesting that claudin-5 expression delineates a specific subset of ependymoma cases." (PMID 27395057, 2017).
Ewing sarcoma (1 paper, 2021). A small round cell tumor that lacks morphologic, immunohistochemical, and electron microscopic evidence of neuroectodermal differentiation. "Ewing sarcoma/primitive neuroectodermal tumor (ES/PNET) cells frequently express epithelial markers such as cytokeratins, claudin-1 and ZO-1, and exhibit a partial epithelial differentiation state." (PMID 34022967, 2021).
experimental autoimmune encephalomyelitis (1 paper, 2019). An autoimmune demyelinating disease of the central nervous system that is produced experimentally in animals by the injection of homogenized brain or spinal cord in Freund's adjuvant. "Furthermore, ectopic expression of claudin-1 has been shown to seal BBB TJs in experimental autoimmune encephalomyelitis." (PMID 29569041, 2019).
gastric diseases (1 paper, 2024). "Moreover, CLDN1 expression was negatively correlated with ANGPTL4 within the H. pylori-infected gastric mucosa of patients and mice along with higher ANGPTL4 in patients with gastric ulcer, suggesting potential roles of gastric mucosal damage of ANGPTL4 in H. pylori-associated gastric diseases." (PMID 39022746, 2024).
glomerulonephritis (1 paper, 2014). A renal disorder characterized by damage in the glomeruli. "In conclusion, our results demonstrate that claudin-1 is expressed in cellular crescents in human glomerulonephritis." (PMID 24868462, 2014). "Their findings, taken together with our results, suggest that claudin-1 contributes to tight junction formation among adjacent proliferating cells in crescentic lesions in human glomerulonephritis." (PMID 24868462, 2014). "Thus, it is possible that formation of tight junction complexes with claudin-1 and ZO-1 in extracapillary proliferating lesions contributes to minimizing the solute-leakage induced interstitial damage by endowing crescents with a barrier property in human glomerulonephritis." (PMID 24868462, 2014).
goiter (1 paper, 2024). Enlargement of the thyroid gland usually caused by lack of iodine in the diet, hyperthyroidism, or thyroid nodules. "Only goiters showed negative claudin-1 and positive claudin-4 staining, similar to those reported in normal thyroid tissues." (PMID 39458944, 2024).
Hailey-Hailey disease (1 paper, 2014). Benign chronic familial pemphigus of Hailey-Hailey is characterized by rhagades mostly located in the armpits, inguinal and perineal folds (scrotum, vulva). "While there have not been reports of tight junction activity in pemphigus patients, it is noteworthy that an upregulation of claudin 1 was found in Hailey-Hailey disease." (PMID 25006807, 2014).
heroin dependence (1 paper, 2021). Physical and psychological dependence on the drug heroin. "The expression of Claudin-1 and ZO-1 were decreased in both heroin dependence and FMT groups and these results indicated intestinal mucosal mechanical barrier impairment." (PMID 34805249, 2021).
influenza infection (1 paper, 2021). "Previous influenza infection was associated with decreased claudin-1 expression in all groups and decreased occludin expression in OVA or HDM-challenged mice." (PMID 34445491, 2021). "This suggests a possible association with influenza infection and sensitization where a compensatory effect of claudin-1 is seen as occludin expression is lost." (PMID 34445491, 2021). "To investigate the direct in vivo effects of influenza infection on barrier integrity, we examined the TJs claudin-1 and occludin, key junctional proteins for the maintenance of epithelial integrity via immunohistochemical staining." (PMID 34445491, 2021). "Increased claudin-1 expression following influenza infection and OVA or HDM challenge in comparison to saline was observed within our study despite intrinsic expression of claudin-1 within the airway epithelium being very low." (PMID 34445491, 2021).
internal carotid artery stenosis (1 paper, 2022). Carotid stenosis is a narrowing or constriction of the inner surface (lumen) of the carotid artery, usually caused by atherosclerosis. "The authors’ research has shown a significant increase in MMP2 and MMP9 activity and a significant increase in the concentrations of claudin-1 and occludin in the blood of patients undergoing the reconstruction of internal carotid artery stenosis." (PMID 35627746, 2022).
intrauterine growth restriction (1 paper, 2022). "Consistent with it, our previous study has found that MFGM promoted the expression of MUC2 and tight junction protein (ZO-1, occuludin, and claudin-1) in intrauterine growth restriction mice." (PMID 35799795, 2022).
iron deficiency (1 paper, 2024). "In this study, iron deficiency and iron overload resulted in downregulation of the tight junction proteins Occludin and Claudin-1 as well as the mucosal proteins MUC1 and MUC2 in jejunum mucosa, which may contribute to a greater susceptibility of neonates to pathogen infection." (PMID 39127747, 2024).
kidney stones (1 paper, 2024). "The most striking finding of our study was the statistically significant increased expression of the CLDN1 gene, which encodes a tight junction protein, in patients with recurrent kidney stones." (PMID 39345805, 2024). "In this study, CLDN1 expression was found to be increased in patients with a history of recurrent kidney stones and to be highly positively correlated with CLDN4, CLDN7 and CLDN14 and moderately correlated with CLDN2 and CLDN8." (PMID 39345805, 2024).
metastatic cancer (1 paper, 2024). A carcinoma which has spread from the original site of growth to another anatomic site. "Moreover, CLDN1 also enhances the efficacy of chemotherapy, so CLDN1 is not only a potential prognostic marker but also a predictive marker for chemotherapy benefits in metastatic cancer." (PMID 38731853, 2024).
myeloma (1 paper, 2023). "Additionally, PKA phosphorylation is known to regulate the subcellular expression of claudin-1 in myeloma cells." (PMID 38114708, 2023).
Nephropathy (1 paper, 2023). A nonspecific term referring to disease or damage of the kidneys. "Thus, we sought to investigate the relationship between SIRT1 and claudin 1 in human kidney biopsies, in an experimental adriamycin (ADR)-induced nephropathy model, and in immortalized mouse podocytes." (PMID 38114708, 2023).
nephrosis (1 paper, 2014). Pathological processes of the KIDNEY without inflammatory or neoplastic components. "Claudin-5 can be found at the apical membrane of the rat podocytes of puromycin aminonucleoside (PAN) induced nephrosis, and claudin-1 can be found in basolateral membrane of rat epididymis." (PMID 24868462, 2014).
nerve sheath tumors (1 paper, 2022). "In our study, we histopathologically reevaluated 79 canine nerve sheath tumors and assessed their reactivity for the immunohistochemical markers Sox10, claudin-1, GFAP, CNPase, and Ki-67." (PMID 35622732, 2022).
neuroblastoma (1 paper, 2025). Neuroblastoma (NB) is the most common solid, extracranial childhood tumor. "In neuroblastoma, EphB4 and CLDN1 are not expressed, but in addition to LAT1, some ROBO1 is expressed." (PMID 40076777, 2025).
odontogenic cyst (1 paper, 2022). A cyst in the jaw that arises from tissues of tooth development. "The objectives of this study were to analyze claudin-1, -4, and -7 expression in different types of odontogenic cysts, COCs, DCs, OKCs, and RCs, as well as its association with OKC recurrence." (PMID 34808689, 2022). "Materials and Methods Seventy samples of odontogenic cysts samples were immunohistochemically stained to detect claudin-1, -4, and -7 expression." (PMID 34808689, 2022). "Our report is the first to study the expression of claudin-1, -4, and -7 in every notable type of odontogenic cyst." (PMID 34808689, 2022). "The expression of claudin-1, -4, and -7 was present in every odontogenic cyst type, but the proportion of cells with positive staining was different." (PMID 34808689, 2022). "High claudin-1 expression was shown in COCs, DCs, and RCs, while low expression of claudin-4 was shown in every odontogenic cyst." (PMID 34808689, 2022). "Every odontogenic cyst type was positive for claudin-7, but the proportion of positive cells was less than that seen for claudin-1." (PMID 34808689, 2022). "Every type of odontogenic cyst had low expression of claudin-4, but claudin-1 and -7 were expressed in every odontogenic cyst." (PMID 34808689, 2022). "Claudin-1 and -4 expression among odontogenic cyst was statistically significantly different." (PMID 34808689, 2022). "Claudin-1 and -4 was significantly different among each odontogenic cyst." (PMID 34808689, 2022).
Oral ulcer (1 paper, 2025). Erosion of the mucous mebrane of the mouth with local excavation of the surface, resulting from the sloughing of inflammatory necrotic tissue. "Following 8 and 12 days of butyrate intervention, transcription levels of ZO-1 and Claudin-1 were significantly upregulated in butyrate-treated mice when compared to the oral ulcer group." (PMID 40818135, 2025). "Transcription levels of tight junction proteins ZO-1 and Claudin-1 were significantly lower in the oral ulcer group compared to the normal group." (PMID 40818135, 2025). "Additionally, immunofluorescence results demonstrated that protein levels of ZO-1 and Claudin-1 were significantly elevated in butyrate-treated mice relative to those with oral ulcers." (PMID 40818135, 2025).
osteoarthritis (1 paper, 2024). A noninflammatory degenerative joint disease occurring chiefly in older persons, characterized by degeneration of the articular cartilage, hypertrophy of bone at the margins and changes in the synovial membrane. "Claudin-1 levels showed a positive correlation with the genus Veillonella, which has been described as elevated in saliva and the synovial fluid of RA patients compared to HCs and osteoarthritis patients, respectively." (PMID 39201334, 2024).
osteoporosis (1 paper, 2024). A condition of reduced bone mass, with decreased cortical thickness and a decrease in the number and size of the trabeculae of cancellous bone (but normal chemical composition), resulting in increased fracture incidence. "Compared with the sham group, the expression of intestinal tight junction proteins ZO-1, claudin-1, and occludin was significantly reduced in the OVX group (p < 0.01), showing that the integrity of the gut barrier of osteoporosis mice induced by OVX was damaged." (PMID 38835486, 2024).
ovarian epithelial tumor (1 paper, 2021). A benign, borderline, or malignant tumor that originates from the surface epithelium of the ovary. "Another study reported CLDN1 was mainly expressed in ovarian epithelial tumors for indication of epithelial differentiation." (PMID 34116704, 2021).
pancreatitis (1 paper, 2024). Inflammation of the pancreas. "In pancreatitis, occludin, claudin-1 and ZO-1 are decreased, but no changes in claudin-4 have been reported; whereas E-cadherin and β-catenin are dissociated from the plasma membrane and condensed in the cytosol of acinar cells." (PMID 39030443, 2024).
paraganglioma (1 paper, 2025). A benign or malignant neoplasm arising from paraganglia located along the sympathetic or parasympathetic nerves. "However, CLDN1 shows marked downregulation in pheochromocytoma and paraganglioma (PCPG) (log2FC = -4.7), and CLDN2 exhibits even more pronounced downregulation in sarcoma (SARC) (log2FC = -10.2)." (PMID 41461671, 2025).
parasitic infection (1 paper, 2021). "The activation of CLDN1 might be associated with the increase in cytokines caused by parasitic infection." (PMID 34108017, 2021).
polyp (1 paper, 2017). A usually exophytic mass attached to the underlying tissue by a broad base or a thin stalk. "We performed immunohistochemical analysis for p63, ΔNp63 and CLDN-1, -4, -7 in normal, sinusitis and polyp (NP) tissues." (PMID 28883651, 2017).
pterygium (1 paper, 2025). A wedge-shaped fibrovascular lesion arising from the bulbar conjunctiva and extending to the cornea. "Additionally, CLDN1 mRNA expression was significantly reduced in pterygium corneal epithelial samples (p = 0.023), and CDH1 mRNA expression was significantly lower in EBMD (p = 0.021) and pterygium corneal epithelial samples (p = 0.003) than in controls." (PMID 40094891, 2025).
rectal cancer (1 paper, 2018). A primary or metastatic malignant neoplasm that affects the rectum. "For instance, the expression of CLDN1 was reduced in stage II and III rectal cancer and was established as a factor that correlates clearly with recurrence and poor prognosis." (PMID 30219077, 2018).
sarcoidosis (1 paper, 2010). Sarcoidosis is a multisystemic disorder of unknown cause characterized by the formation of immune granulomas in involved organs. "Claudin-1 was, however, detected in the metaplastic alveolar epithelium of IPF and sarcoidosis." (PMID 20478039, 2010).
sinusitis (1 paper, 2017). An acute or chronic inflammatory process affecting the mucous membranes of any sinus cavity. "In the present study, p63, ΔNp63, HDAC1 and HDAC6 were upregulated and CLDN-1 and -4 were downregulated in the epithelium of sinusitis and NPs." (PMID 28883651, 2017). "CLDN-1 and CLDN-4 were downregulated in the sinusitis and NPs, whereas no change of CLDN-7 was observed in sinusitis or NPs." (PMID 28883651, 2017).
spindle cell tumors (1 paper, 2022). "On the basis of our results, we agree with previous studies in human and veterinary medicine that have shown that claudin-1 in combination with other antibodies could serve as a useful marker to distinguish NSTs from other spindle cell tumors and, moreover, to subclassify NSTs." (PMID 35622732, 2022).
ulcer (1 paper, 2025). "mRNA levels of IL-1β, IL-6, IL-18, and TNF-α in the ulcer tissue were significantly reduced following butyrate treatment, while the levels of tight junction proteins Claudin-1 and ZO-1 were significantly elevated." (PMID 40818135, 2025). "Moreover, sodium butyrate promoted the mRNA and protein expressions of tight junction protein-1 (ZO-1) and Claudin-1 in the epithelial cells of the ulcer tissue." (PMID 40818135, 2025).
undifferentiated thyroid carcinomas (1 paper, 2024). "Furthermore, claudin-1 was overexpressed in papillary thyroid cancer, while claudins 1, 4, and 7 were underexpressed in undifferentiated thyroid carcinomas." (PMID 39458944, 2024).